RNU4-25P (RNA, U4 small nuclear 25, pseudogene)
Gene: Small nuclear RNA gene on chromosome 8 (128,010,382 to 128,010,611, reverse strand). Ensembl gene ENSG00000222501.
Homologues: Orthologues: chimpanzee U4 (98% identical), macaque U4 (93% identical), dog U4 (35% identical), dog U4 (33% identical), tropical clawed frog U4 (30% identical), dog U4 (28% identical), rat LOC120102559 (26% identical). Paralogues in human: RNU4-53P (37% identical), RNU4-22P (36% identical), RNU4-40P (34% identical), RNU4-48P (34% identical), RNU4-72P (33% identical), RNU4-6P (33% identical), RNU4-89P (33% identical), RNU4-91P (33% identical), RNU4-4P (33% identical), RNU4-5P (33% identical), RNU4-82P (33% identical), RNU4-36P (32% identical), and 80 more.
Diseases named in the same sentence as RNU4-25P in open-access papers:
RNU4-25P is named in the same sentence as 1 disease in open-access papers, as found by Europe PMC text mining. Sharing a sentence is not in itself a finding about the gene and the disease.
RNU4-25P shares sentences with these, for which no sentence is quoted: tumor (1 paper).